PTTG1 (PTTG1 regulator of sister chromatid separation, securin)
Diseases named in the same sentence as PTTG1 in open-access papers (continued):
Sharing a sentence is not in itself a finding about the gene and the disease.
cancer (continued). "In order to confirm the high expression of PTTG1 in ESCC tissues, we collected ESCC tissues and their matched non-cancer tissues from eight clinical patients with ESCC and obtained in-house RNA-seq data of these samples." (PMID 33552118, 2020). "Further analysis of public RNA-seq data showed that the average expression of PTTG1 in ESCC was 11.5794 ± 0.7270, which was significantly higher than that of the non-cancer control group (7.5575 ± 2.5127, P < 0.001)." (PMID 33552118, 2020). "After research, it was found that the expression of PTTG1 in four high-throughput platforms (GPL570, GSE23400, GSE70409, and TCGA-GTEx) was significantly higher than in the non-cancer control group." (PMID 33552118, 2020). "We revealed mRNA expressions of PTTG1, PTTG2, and PTTG3 which also named as PTTG3P in 20 types of cancers." (PMID 33173433, 2020). "In this study, we identified that PTTG1 acted as a promoter in inducing EMT and cancer metastasis in ESCC via activating GLI1, an important factor of the HH-GLI signaling pathway." (PMID 29190924, 2017). "PTTG1 had been reported to play an important role in EMT and here we also confirmed that PTTG1 induced EMT in ESCC cells and then promoted cancer metastasis." (PMID 29190924, 2017). "Thus, PTTG1 may represent a molecular marker of or a potential therapeutic target for many cancers." (PMID 23977008, 2013). "PTTG1, also known as human securin, regulates key processes such as cell cycle progression, apoptosis suppression, and EMT, promoting metastasis and enhancing cancer cell survival." (PMID 40072059, 2025). "To conclude, PTTG1 and RAC2 are critical regulators of cancer progression and promising targets in anticancer therapy due to their roles in EMT, signaling pathways like TGF-β, PI3K/AKT, and NF-κB, as well as their influence on immune evasion and therapy resistance." (PMID 40072059, 2025). "The overexpression of PTTG1 could promote the resistance to ADT in CRPC via inducing EMT and increasing the cancer stem cell population." (PMID 38887275, 2024). "Notably, we also found a cluster of cells that exhibited higher expression of a set of cell cycle-related genes (CENPF, NUSAP1, PTTG1, STMN1, TOP2A, and TUBA1B), which was consistent with proliferative CAFs (pCAFs) in a previous pan-cancer study of CAFs." (PMID 37833788, 2023). "Moreover, pan-cancer patients with upregulated PLK1, CEP55, FANCI, NEK2, and PTTG1 exhibited a poorer overall survival rate and disease-free survival." (PMID 37274251, 2023). "In addition, gene network analysis regarding to mass-type ER-positive cancers showed that ESR1, BIRC5, CAV1, FGFR1, IL6, MIR27, and PTTG1 were upregulated." (PMID 37391754, 2023). "Therefore, its absence enhances PTTG1 expression and the consequent proliferation, EMT, migration, and invasion of HCC cancer cells." (PMID 35805898, 2022). "All these results indicated that PTTG1 showed the same trends of expression and poor outcome as PRR11 and may be an oncogene in pan-cancer." (PMID 36060253, 2022). "We need to remember that patients with low expressions of PTTG3P, PTTG1 and PTTG2 have cancer." (PMID 32824814, 2020). "To validate whether the candidate targets can actually interrupt cancer progression, we perform in vitro knockdown of CCDC85B and PTTG1 using siRNA and examine the changes of the growth rate and transcriptomic levels." (PMID 33133158, 2020). "PTTG1 has been shown to transcriptionally activate expression of a wide range of target genes, including c-Myc, FGF-2, cyclin D3, p21, and MMP-2, most of which are critically involved in cancer proliferation and metastasis." (PMID 33250768, 2020). "It proves that PTTG3P, PTTG1 and PTTG2 may function as oncogenes in HNSCC, similarly as was indicated in other cancers." (PMID 32824814, 2020). "Furthermore, studies in cell lines suggests that cancer cells depend on a functional mitotic checkpoint and increased expression of CCNB1 and PTTG1 is therefore more likely a result of increased proliferation." (PMID 31801961, 2020).
cancer (continued). "Moreover, using the Cancer Genome Atlas database, we observed that the expression of the APC substrate genes PTTG1 and DLGAP5 in cancer patients is differentially regulated between normal tissues and tumor tissues, across 24 different types of cancer." (PMID 29954095, 2018). "Recently, researchers have shown that PTTG1 could cooperate with some signaling pathway, such as: Rho/ROCK and RAS-MAPK to induce EMT and promote tumorigenesis in cancers." (PMID 29190924, 2017). "Furthermore, we also showed that PTTG1 promoted EMT and cancer metastasis in ESCC cell lines at least via the activation of GLI1." (PMID 29190924, 2017). "Both PTTG1 and PTTG2 have been reported to serve oncogenic functions in human cancers 9, 10, 11, but the role of PTTG3P in GC remains unclear, and this pseudogene has previously been regarded as functionless." (PMID 28631396, 2017). "Our results suggested that PTTG1 was a promoter in EMT in ESCC and PTTG1 might be an attractive target for cancer metastasis." (PMID 29190924, 2017). "We found that SP17, AKAP4 and PTTG1 are aberrantly expressed in cancer samples, compared to normal lung cell lines and tissues." (PMID 25739119, 2015). "Indeed, PTTG1 has been shown to transcriptionally activate expression of a wide range of target genes, including c-Myc, FGF-2, cyclin D3, p21, and MMP-2, most of which are critically involved in cancer proliferation and metastasis." (PMID 33250768, 2020). "Hence, we detected a significant up-regulation of PTTG1 in malignant squamous cells from an independent set of ISCC that confirms the obtained array data and is in line with previously published PTTG1 expression in lung and other cancers." (PMID 28073359, 2017). "The results revealed that radiation increased the ratio of MAP1LC3-II/MAP1LC3-I in MDA-MB-231-2A cells (PTTG1-knockdown MDA-MB-231 cells) and MCF-7 cells (low PTTG1 expression), but not in the parental MDA-MB-231 cells, suggesting that radiation induced autophagy in PTTG1-depleted cancer cells." (PMID 25317422, 2014). "Notable exclusions include the cancer/testis antigens MAGEA1, MAGEA3, MAGEA6, GAGE1, GAGE2, GAGE4 and GAGE5, which were originally identified as being strongly upregulated in the PR subgroup but are not upregulated in our PTTG1 high patients." (PMID 26445238, 2015).
adenocarcinoma (3 papers, 2006 to 2020). A common cancer characterized by the presence of malignant glandular cells. "In line with our results a PTTG-1 expression was observed in 9 out of 10 primary adenocarcinomas of the lung using immunohistochemial methods." (PMID 16426442, 2006). "Notably, 4 of the glucose metabolism-related genes, GPI, G6PD, PKM2, and GAPDH and 5 of the cell cycle-related genes, ANLN, PTTG1, CIT, KPNA2, and CDC25A, were significantly down-regulated in EGFR m+ adenocarcinomas, and showed a substantial correlation with SUVmax." (PMID 28422979, 2017).
infection (3 papers, 2021 to 2023). The state of being infected such as from the introduction of a foreign agent such as serum, vaccine, antigenic substance or organism. "The overall downregulation of genes following infection of BALB/c mice is dominated by Mpeg1 and Pttg1." (PMID 33816350, 2021).
hematological malignancies (2 papers, 2013 to 2018). "Our results suggest that drugs that increase the activities of KLF6 may inhibit the transcription of PTTG1 and have the potential to be used as a therapeutic tool for hematopoietic diseases." (PMID 23977008, 2013).
PTTG1 also shares sentences with these, for which no sentence is quoted: adrenocortical cancer (3 papers); osteosarcoma (3); corticotroph adenomas (2); gastrointestinal tumor (2); invasive ductal carcinoma (2); lymphoid neoplasm (2); metastatic tumors (2); neuroendocrine tumor (2); pituitary cancer (2); anaplastic thyroid cancer (1); choriocarcinoma (1); diffuse large B-cell lymphoma (1); gastric adenocarcinoma (1); gonadotroph adenomas (1); gynecologic tumors (1); head and neck cancer (1); head and neck squamous cell carcinoma (1); heart failure (1); hematopoietic neoplasms (1); HIV-1 infection (1); hyperprolactinemia (1); Insulin resistance (1); kidney tumors (1); leiomyosarcoma (1); Lymphadenopathy (1); mesothelioma (1); metastatic prostate carcinoma (1); non-functioning pituitary adenoma (1); Obesity (1); oral squamous cell carcinoma (1).
A further 25 diseases each share a sentence with PTTG1 in 1 paper.